ATM (ATM serine/threonine kinase)
Diseases named in the same sentence as ATM in open-access papers (continued):
Sharing a sentence is not in itself a finding about the gene and the disease.
prostate tumors (9 papers, 2018 to 2025). "BRCA2- or ATM-deficient prostate tumors exhibit heightened sensitivity to PARP inhibitors via synthetic lethality." (PMID 40427518, 2025). "While BRCA2- and ATM-mutated prostate tumors often exhibit more pronounced susceptibility to PARP blockade, some cases without BRCA mutations also display partial responses." (PMID 40427518, 2025). "Furthermore, our results show that Andrographolide increased the expression of ataxia-telangiectasia mutated (ATM) in prostate tumors." (PMID 30800220, 2019). "We employed 14 patient-derived tumor graft models pancreatic, lung, and prostate tumor graft models harboring HR mutations (BRCA1/2, CHK1/2, ATM/ATR, PALB2, PARP1/2, RAD51, FANCA/B) to compare LP-184’s potency with PARPi olaparib." (PMID 38630886, 2024). "We also found that somatic mutations in BRCA2, NEIL3, ATM, and ATR were associated with higher mutational burden in prostate tumors." (PMID 32300177, 2020). "The up-regulation of ATM by N-Myc overexpression in C4–2 cells is further confirmed by IHC staining of N-Myc and ATM in different stages of human prostate tumor tissues." (PMID 30657058, 2019). "Prostate tumors may harbor a spectrum of DDR alterations beyond those in BRCA1/2, including those in ATM and other HR-associated genes." (PMID 40427518, 2025). "The Cancer Genome Atlas (TCGA) analysis of 333 primary prostate tumors revealed BRCA2 and BRCA1 mutation rates that were quite similar to our study (3% and 1%, respectively), while ATM mutations were slightly more frequent than in our study (4% in TCGA vs. 1% in our study)." (PMID 38256334, 2023). "In addition, they found a trend toward increased ATM expression in high‐grade (Gleason 8–10) prostate tumors compared to low‐ and intermediate‐grade (Gleason 6&7)." (PMID 29845714, 2018). "In addition, Andrographolide decreased prostate tumor growth, decreased matrix metalloproteinase 11 (MMP11) expression, decreased angiogenesis and altered DNA repair genes such as BRCA2, ATM, BRIP1 in vivo." (PMID 30800220, 2019). "On the other hand, as no loss of MSH6 expression was observed in the prostate tumor, this MSH6 variant is unlikely to explain the PrCa predisposition in this family, which is most likely related to the RAD51C truncation mutation or the ATM missense mutation also found in this patient." (PMID 29659569, 2018).
retinoblastoma (9 papers, 2015 to 2024). A malignant tumor that originates in the nuclear layer of the retina. "Regarding ATM, it was recently reported that cells from retinoblastoma patients with germline RB mutations demonstrate radiation sensitivity, presumably through an impact on ATM." (PMID 35719921, 2022). "Immediately downstream effects include reduced c-myc expression, increased p-H2A.X, and decreased ATM expression, resulting in caspase-dependent apoptosis that is associated with decreased retinoblastoma expression and cleaved c-abl." (PMID 31570763, 2019). "In mammals BRCA1 interacts with MRN (MRE11-RAD50-NBS1), CtIP (COM1-SAE2), and Retinoblastoma, to activate G2 cell cycle check-point by means of ATM phosphorylation." (PMID 26147458, 2015). "Interestingly cells from cancer syndromes show either a maximal number of MRE11 foci from 10 min to 1 h after 2 Gy X-rays (e.g., retinoblastoma, tuberous sclerosis complex, and neurofibromatosis type 1) or the MRE11 foci are impaired (e.g., in BRCA1-, BRCA2-, BLM-, FANC-, and ATM-mutated cells)." (PMID 37626928, 2023). "The ATM tumor suppressor gene was significantly altered in cases with 11q deletion, which has not yet been described in retinoblastoma." (PMID 33567541, 2021). "In addition, the use of WBC sequencing revealed the germline origin of observed copy number deletions in ATM, BRCA2, and for two patients with retinoblastoma, RB1, based on deletions in their matched WBC sample." (PMID 34145282, 2021).
skin cancer (9 papers, 2017 to 2025). "Therefore, tRA combined with the ATM inhibitor might improve the efficiency of protecting skin from angiogenesis-associated pathologies, including skin aging and skin tumors." (PMID 31766690, 2019). "ATM variants follow autosomal dominant inheritance and encode a kinase activated by DNA damage, including UVR—a key factor in skin cancer development." (PMID 41331641, 2025). "The evidence linking BRCA1/2, ATM, CHEK2, BRIP1, and FH pathogenic variants to increased skin cancer risk is limited." (PMID 41331641, 2025). "This review consolidates existing evidence and suggests that mixed cancer syndromes, especially LFS, LS, and HBOC but also pathogenic ATM and CHEK2 variants may predispose individuals to skin cancers, warranting tailored screening and preventive measures." (PMID 41331641, 2025). "Also, in skin cancer, more specifically in Merkel cell carcinoma (MCC), a highly aggressive skin cancer which is associated with chronic exposure to UV, 29% of patients showed abnormalities in DNA repair genes, such as ATM." (PMID 35326410, 2022).
ataxia-telangiectasia-like disorder (8 papers, 2010 to 2022). An autosomal recessive condition caused by mutation(s) in the MRE11A gene, encoding double-strand break repair protein MRE11. "The effects of ATM/ATR are focused on ataxia-telangiectasia-like disorders and malignancies." (PMID 35176943, 2022).
Glucose intolerance (8 papers, 2017 to 2025). Glucose intolerance (GI) can be defined as dysglycemia that comprises both prediabetes and diabetes. "N-Acetyl Cysteine rescues glucose intolerance, glutamate accumulation and glucagon production in the pancreatic islets of ATM-deficient mice." (PMID 39281865, 2024). "In a previous study, administering EVs derived from adipose tissue Mφ (ATM-EVs) from obese mice to lean mice caused glucose intolerance and IR, while administering lean mice ATM-EVs to obese mice improved glucose tolerance and insulin sensitivity." (PMID 34975877, 2021). "Therefore, ATM deficiency leads to impaired adipocyte differentiation, which impairs adipokine secretion, resulting in IR and glucose intolerance." (PMID 36354755, 2022). "Low ATM levels will therefore contribute to the development of IR and glucose intolerance in A-T via the down-regulation of Akt activity in muscle cells." (PMID 32733823, 2020).
neurofibromatosis type 1 (8 papers, 2018 to 2025). A clinically heterogeneous, neurocutaneous genetic disorder characterized by cafe-au-lait spots, iris Lisch nodules, axillary and inguinal freckling, and multiple neurofibromas.
Seckel syndrome (8 papers, 2014 to 2022). A rare autosomal recessive inherited syndrome caused by mutations in the ATR gene, RBBP8 gene, CENPJ gene, CEP152 gene, CEP63 gene, NIN gene, DNA2 gene, or TRAIP gene. "While hypomorphic mutations in ATR and ATM genes have been identified among patients carrying Seckel syndrome and A-T, respectively, little was known about mutations in DNA-PKcs encoding RPKDC gene in human until recently." (PMID 24500207, 2014). "ATR may be more essential than ATM for cell viability since only punctual mutations of ATR have been observed: such ATR mutations cause Seckel syndrome (or microcephalic primordial dwarfism (SCKL))." (PMID 36551628, 2022). "Seckel syndrome has the ATM gene related to its potential drug target." (PMID 36141396, 2022).
small cell lung carcinoma (8 papers, 2017 to 2025). Small cell lung cancer (SCLC) is a highly aggressive malignant neoplasm, accounting for 10-15% of lung cancer cases, characterized byrapid growth, and early metastasis. "Bavachinin activates ATM to induce apoptosis in small cell lung cancer cells." (PMID 37208425, 2023).
Werner syndrome (8 papers, 2010 to 2025). "A similar approach targeting DDR via ATM inhibitors or telomeric noncoding RNAs has shown promise in other syndromes of premature aging, such as Hutchinson-Gilford progeria and Werner syndromes." (PMID 40179146, 2025). "First, we examined CHK1 phosphorylation at Ser345 in an isogenic pair of uncorrected and WRN wild-type-corrected (WSWRN) SV40-transformed Werner syndrome (WS) fibroblasts, in which ATM (ATMi), ATR (ATRi) or both (ATMi/ATRi) were chemically inhibited." (PMID 30657978, 2019).
cataract (7 papers, 2017 to 2024). Partial or complete opacity of the crystalline lens of one or both eyes that decreases visual acuity and eventually results in blindness. "In addition, early cataracts and retinal and choroidal vascular abnormalities (irradiated peripheral telangiectasia) were also found to be associated with ATM variation." (PMID 33294447, 2020). "We have previously reported that histone acetyltransferase (HAT) and ATM inhibitors decrease opacity in the galactose-induced cataract model." (PMID 38416732, 2024). "Homozygous “T” allele carriers of ATM-rs4585 had more DNA breaks compared to “G” allele carriers in ARC, cortical, posterior subcapsular and mixed cataract patients (P< 0.05)." (PMID 29156695, 2017). "Indeed, it has been showed that mice homo- and heterozygous for the DNA repair genes ATM, BRCA1 and RAD9 develop cataracts earlier and in greater numbers." (PMID 33303795, 2020).
familial breast cancer (7 papers, 2004 to 2024).
fibrosarcoma (7 papers, 2009 to 2021). A malignant mesenchymal fibroblastic neoplasm affecting the soft tissue and bone. "The role of STAT3 in DNA damage has been highlighted in fibrosarcoma, where cells with low STAT3 levels have decreased ATM-Chk1 and ATM-Chk2 via transcriptional regulation of MDC1." (PMID 29262529, 2017).
fibrosis (7 papers, 2016 to 2023). the formation of excess fibrous connective tissue in an organ or tissue in a reparative or reactive process. "The loss of ATM reduces hepatocyte apoptosis and fibrosis, suggesting that the activation of ATM in response to oxidative stress plays a role in hepatic fibrosis development." (PMID 36899918, 2023). "As fibrosis generally precedes the development of hypertrophy, it is possible that the increased basal cardiac fibrosis and hypertrophy are serving as a protective mechanism against WD‐induced cardiac dysfunction in female ATM‐deficient mice." (PMID 36117462, 2022). "In both cell cultures, namely, oxygen-glucose-deprivation (OGD)-treated CMs and H9c2 cells and an in vivo MI mouse model, miR-26a overexpression decreases collagen 1, CTGF, and ATM (Ataxia-telangiectasia mutated) expression levels, reducing cardiac fibrosis and apoptosis." (PMID 36975887, 2023).
Hyperglycemia (7 papers, 2014 to 2025). An increased concentration of glucose in the blood. "We investigated the roles of DNA‐PKcs, Ku80, and ATM in hyperglycemia‐induced DDR within the heart." (PMID 40279648, 2025). "Western blot analysis revealed that phosphorylation of DNA‐PKcs and Ku80 was significantly elevated in diabetic hearts in a dose‐dependent manner, while ATM phosphorylation showed no significant change in response to hyperglycemia." (PMID 40279648, 2025).
invasive ductal carcinoma (7 papers, 2014 to 2024). "The moderate-penetrance gene ATM, is mutated in 1–2% of BC, while in our study it has been found mutated only once (1/200) in a patient with multifocal infiltrating ductal carcinoma." (PMID 34026625, 2021). "The most common histological subtype was infiltrative ductal carcinoma, and the most common molecular subtype was Luminal B. When patients were compared according to variant classifications of ATM mutation, patients' histological and molecular subtypes were similar." (PMID 38021491, 2023). "The most common histological subtype was infiltrating ductal carcinoma in all ATM variant groups." (PMID 38021491, 2023). "In fact, ATM is also up regulated in cases of sclerosing adenosis (SA), a benign proliferative disease of the breast, which is an independent risk factor for subsequent invasive ductal carcinomas." (PMID 25403427, 2014). "In another ATM case we identified a partial skipping of exon 19 (r.3061_3077del) in a Caucasian female diagnosed with invasive ductal carcinoma of the breast at the age of 33 years." (PMID 32133419, 2020).
lung fibrosis (7 papers, 2007 to 2022). "Of interest, RAGE-knockout mice, ATM-deficient mice, and other mouse models with persistent DSB signaling have been shown to develop pulmonary fibrosis, suggesting that DSB accumulation may be a trigger of profibrotic pathways." (PMID 33123169, 2020). "Therefore, structural studies may help reveal the details of ATM regulation in pulmonary fibrosis." (PMID 31248154, 2019). "Our findings further reveal ATM downregulation in chimeric-CD44KO mice, who attenuate lung fibrosis and thus increase tissue regeneration." (PMID 31591327, 2019).
metastatic colorectal cancer (7 papers, 2019 to 2024). "The olaparib/irinotecan combination was used in a heavily pretreated metastatic colorectal cancer patient with an ATM mutation who obtained stable disease for 3 months with a longer clinical and serologic markers improvement." (PMID 36079062, 2022). "This is supported by the report from advanced metastatic colorectal cancer, in which patients with intact ATM (85%: 192 of 227 patients) had significantly poor overall survival compared with those with ATM mutations (15%: 35 of 227 patients)." (PMID 34545188, 2021). "A patient with metastatic colorectal cancer harboring molecular aberrations, including ATM loss and an ARID1A mutation, achieved RECISTv1.1 complete response and maintained this response, with a progression-free survival of 29 months at last assessment." (PMID 32568634, 2020). "Among 227 metastatic colorectal cancer, ATM mutations (15%) were correlated with superior OS." (PMID 38909137, 2024). "In addition, a recent study showed that a metastatic colorectal cancer patient with ATM loss of function mutation benefited from an ATR inhibitor M6620 (VX‐970) monotherapy." (PMID 36161776, 2023). "Other series have shown an ATM mutation prevalence of 15% in metastatic colorectal cancer but no increased prevalence in BRAF mutated cases compared to BRAF wild type metastatic colorectal cancers." (PMID 36079062, 2022).
myelodysplastic syndrome (7 papers, 2016 to 2025). A clonal hematopoietic disorder characterized by dysplasia and ineffective hematopoiesis in one or more of the hematopoietic cell lines. "Surprisingly, the case of myelodysplastic syndrome that occurred in a lung transplant recipient was found to have both ATM somatic variant and a pathogenic DDX41 germline variant." (PMID 36853803, 2023).
progeria (7 papers, 2015 to 2022). "Given that progeria cells exhibit deficiencies in ATM and SIRT6 function, the authors investigated the possibility of using chloroquine to improve aging phenotypes in vitro and in vivo." (PMID 32046343, 2020). "Thus, our data highlights a pro-longevity role of ATM, for the first time establishing direct causal links between robust DNA repair machinery and longevity, and providing therapeutic strategy for progeria and age-related metabolic diseases." (PMID 29717979, 2018). "Studies done in mouse models of lamin A/C-related progerias reveal extensive connections between lamin A/C and ATM." (PMID 35721517, 2022). "Boosting ATM activity extends lifespan in a mouse model of progeria, thus emphasizing the relevance of the accumulation of γH2AX foci to alleviating aging." (PMID 31289256, 2019). "Nevertheless, the activation of ATM via CQ remarkably improves glucose homeostasis, DNA damage clearance, and running endurance, and extends lifespan in progeria mice." (PMID 29717979, 2018). "This was a novel correlation in progeria and was in agreement with previous studies that H3K9me3 was crucial for ATM activation upon DSBs." (PMID 27907109, 2016). "In addition to this, known genes involved in segmental progeroid syndromes are also dysregulated, including ATM and LMNA." (PMID 26176221, 2015). "Classical pathways associated with metabolic alterations in other diseases are beginning to be interrogated in progeria, including mTOR, AMPK, Sirtuins, mitochondrial function, and most recently ATM signaling." (PMID 32046343, 2020).
serous ovarian cancer (7 papers, 2016 to 2023). "A recent report using 17 primary serous ovarian cancer patients and in vitro models showed that EZH2 loss drives resistance to carboplatin and paclitaxel in serous ovarian cancers that express Ataxia Telangiectasia Mutated (ATM)." (PMID 36230683, 2022). "Approximately 50% of high-grade serous ovarian cancers are characterized by HR deficiency, which involves mutations in BRCA1/2, the MRN complex (MRE11, RAD50, NBS1), ATM, RAD51C/D, PALB2, BRIP1, BARD1, and other genes." (PMID 31572446, 2019).
stomach cancer (7 papers, 2015 to 2025). "Since gastric tumours are extremely heterogeneous, PARPis may have higher efficiency in gastric tumours with specific biomarkers, such as the use of ATM loss as a predictive biomarker of tumour response." (PMID 37568604, 2023).